MIR194-1 (microRNA 194-1)
Synonyms: hsa-mir-194-1; MIRN194-1; mir-194-1
Gene: MicroRNA gene on chromosome 1 (220,118,157 to 220,118,241, reverse strand). Ensembl gene ENSG00000207624.
Gene Ontology:
Biological process: miRNA-mediated post-transcriptional gene silencing
Cellular component: RISC complex
Homologues: Orthologues: chimpanzee ptr-mir-194 (100% identical), macaque mml-mir-194-1 (100% identical), rat Mir194-1 (79% identical), pig ssc-mir-194b (76% identical), tropical clawed frog xtr-mir-194-1 (75% identical), rabbit MIR194-1 (67% identical), dog MIR194 (66% identical), mouse Mir194-1 (64% identical), zebrafish mir194a (59% identical), zebrafish mir194b (52% identical).